INS (insulin)
Diseases named in the same sentence as INS in open-access papers (continued):
Sharing a sentence is not in itself a finding about the gene and the disease.
diabetes (continued). "In conclusion, the decrease in insulin/Igf signaling induces Foxo1 and Gsk-3β function, resulting in impaired replication and enhanced β-cell death at transcription and protein levels, respectively, ultimately leading to postnatal β-cell loss and diabetes." (PMID 36361703, 2022). "Both interventions were found to be equally good at a weight and showed improvement in risk markers of CVDs, cancer, and diabetes for example reduction in leptin, leptin to adiponectin ratio, inflammatory markers, fasting insulin, insulin resistance, blood pressure, and lipids." (PMID 35866077, 2022). "Although the gene products at CDKN2A/B play roles in many cell types, strong evidence links CDKN2A/B T2D risk-polymorphisms specifically to impaired insulin secretory function in humans, pointing to impact on pancreatic islets as the causative mechanism by which this gene locus drives diabetes risk." (PMID 35546161, 2022). "The final CKD risk factors consisted of age, duration of diabetes, insulin use, estimated glomerular filtration rate, albumin-to-creatinine ratio, high-density lipoprotein cholesterol, triglyceride, diabetes retinopathy, variation in HbA1c, variation in FPG, and hypertension drug use." (PMID 35314714, 2022). "Early detection of the percentage of insulin-producing cells preceding loss of function would allow for effective therapeutic interventions that could delay or slow down the onset of diabetes." (PMID 36361633, 2022). "Notably, miR-342 (–/–) mice fed with HFHS chow had lower blood glucose levels and fat weight and higher insulin and leptin sensitivity, which suggested that the loss of miR-342 can protect against obesity and diabetes." (PMID 36438765, 2022). "There are also genetic models, like Akita (Insulin mutations leading to loss of beta cells and insulin production mimicking type I diabetes), db/db (Leptin Receptor mutation leading to obesity and diabetes), Kimba (trVEGF029) and Akimba (cross between Akita and Kimba)." (PMID 35453951, 2022). "Insulin use was associated with increased risk of cancer among all cumulative dosage and duration categories based on analysis of 108,920 patients with newly diagnosed diabetes." (PMID 35158824, 2022). "The causes of hypoglycemia in people with diabetes, include:Changes to insulin regimen." (PMID 35858952, 2022). "Thus, homozygous deletion of PTF1AenhP in mice led to pancreatic hypoplasia and insulin-deficient neonatal diabetes." (PMID 35998583, 2022). "Intensive treatment of insulin-dependent diabetes patients—which includes regular insulin treatment, self-monitoring of blood glucose levels, and regular measurement of HbA1c—has been shown to reduce the progression of complications associated with diabetes." (PMID 35501880, 2022). "The American Diabetes Association (ADA) divides diabetes technology into two basic categories: for administration of insulin, e.g., via insulin pens or pumps, and for the analysis of glucose concentrations, e.g., via glucose meters or continuous glucose monitors (CGM)." (PMID 35673501, 2022). "Diabetes mellitus is a comprehensive expression to identify a condition of chronic hyperglycemia whose causes derive from different metabolic disorders characterized by altered insulin secretion or faulty insulin effect on its targets or often both mechanisms." (PMID 35216512, 2022). "However, moderate intensity physical activity including simple interval walking activities can increase insulin uptake in the muscles leading to higher insulin sensitivity and lower risk of diabetes." (PMID 35992098, 2022). "The study suggested that intensive blood-glucose control by either sulphonylureas or insulin could substantially decrease the risk of microvascular complications in patients with type 2 diabetes." (PMID 35795563, 2022). "Additionally, the pattern of increased risk in association with insulin treatment was observed in women with subsequent diabetes." (PMID 36085031, 2022).
diabetes (continued). "The insulin secretion ability of pancreatic β-cells is essential for blood glucose homeostasis maintenance, and the dysfunction of the insulin response is the cause of both forms of diabetes mellitus (type 1 diabetes [T1D] and type 2 diabetes [T2D])." (PMID 35862726, 2022). "Data from a full epigenome association study showed that CpG hypermethylation near PRDM16 in the offspring of mothers with T2DM during pregnancy (OMD) also predicted future diabetes risk, impacting insulin secretion, increased body weight, and increased risk of developing T2DM." (PMID 35462933, 2022). "Besides, as one of the typical characteristics of diabetes, the causal association between insulin level and AD was also included in this study." (PMID 35272707, 2022). "Additionally, several human insulin mutations were found to induce insulin misfolding, ER stress, β-cell failure, and diabetes, similar to those of the Akita mouse model." (PMID 35563231, 2022). "In addition, specific behaviours and attitudes related to diabetes, such as dietary restriction, counting carbohydrates and insulin injection impose an additional risk for DEB." (PMID 35379350, 2022). "Diabetes is a complex metabolic disorder of carbohydrate metabolism, characterized by high blood glucose levels either due to an absolute deficiency of insulin secretion or an ineffective response of cells to insulin, a hormone synthetized by β-cells in the pancreas." (PMID 35966093, 2022). "Those at risk for diabetes have a reduced degradation rate of insulin." (PMID 35163746, 2022). "In addition, studies have suggested that physical activity prevents type 2 diabetes mellitus—a known risk factor for periodontal diseases—by improving insulin sensitivity." (PMID 35409556, 2022). "Insulin has an important role in managing obesity and is associated with diabetes." (PMID 35268815, 2022). "Additionally, the high-risk group had higher prevalence of insulin-treated diabetes mellitus, anemia, CKD, dialysis, peripheral artery disease and atrial fibrillation." (PMID 36099321, 2022). "Although we hypothesized that a low-AGE diet would improve insulin sensitivity and therefore decrease the risk of future diabetes, a decreased abundance of Anaerostipes is suggestive of a more diabetes-prone phenotype." (PMID 35628138, 2022). "Type 2 diabetes mellitus (T2DM) is a condition in which there is too much glucose circulating in the blood because of long-standing increases in insulin resistance leading to the eventual deficiency in insulin responsiveness to hyperglycaemia." (PMID 35276999, 2022). "Diabetes mellitus is a chronic multi-systemic metabolic disease characterized by hyperglycemia due to either a deficiency of insulin secretion or resistance to the action of insulin or both." (PMID 35267672, 2022). "On the other hand, studies of women with gestational diabetes, diabetes mellitus or obesity show that the risk of preeclampsia, caesarean section or preterm birth is lower or similar when the effect of metformin is compared to the placebo or to insulin." (PMID 35130922, 2022). "Diabetes mellitus (DM) is a group of metabolic disorders of different etiologies that are associated with insufficient secretion of insulin from the β-cells of the pancreatic islets and variable degrees of peripheral insulin resistance, resulting in hyperglycemia." (PMID 36142532, 2022). "The pathophysiology of CFRD is complex and distinct from other forms of diabetes, but insulin deficiency secondary to damaged islets is the primary mechanism, with insulin resistance and incretin axis abnormalities also implicated to a lesser and more variable extent." (PMID 36382232, 2022). "Diabetes mellitus (DM) is a complex metabolic disorder characterized by a chronic presence of hyperglycemia and glycosuria as the results of insulin deficiency or impaired insulin response to target tissues." (PMID 35650303, 2022).
diabetes (continued). "Although the LAP’s ability to discriminate excess visceral fat is still little explored, studies indicate greater specificity of the LAP in the prediction of type 2 diabetes mellitus, metabolic syndrome, resistance to insulin, and risk of cardiovascular diseases when compared to BMI." (PMID 35564900, 2022). "What’s more, insulin could stimulate cellular iron intake and redistribute TfR1 to cell surface, which may explain the association between sTfR levels and diabetes as well as insulin resistance." (PMID 35493097, 2022). "SWS inhibition in young healthy adults could even reduce insulin-sensitivity, impair glucose tolerance, and increase the risk of diabetes." (PMID 36386313, 2022). "Because of the risk of hypoglycemia, insulin and other medications used to treat diabetes may need dose adjustment as kidney failure progresses." (PMID 35329847, 2022). "Considering the link between DM and oxidative stress, it can be said that this plant part can be a good phytoantioxidants agent to hamper oxidative stress caused by diabetes and could even improve insulin sensitivity." (PMID 35335362, 2022). "This perpetuating cycle may also explain how the overabsorption of nutrients might increase GIP to such levels that it would overstimulate insulin secretion that would potentially cause insensitivity and diabetes." (PMID 35224107, 2022). "This essential element has functions that may counteract diabetes-related risk factors and complications, which include stabilization of insulin hexamers and pancreatic insulin storage and improved glycemic control." (PMID 35405968, 2022). "Another potential hypothesis of the negative association between SUA and HbA1c among subjects with diabetes was about insulin." (PMID 36464722, 2022). "Our previous study has found that short-term intensive insulin therapy in patients with newly diagnosed type 2 diabetes mellitus (T2DM) increased serum testosterone levels, but the underlying mechanisms remain unclear." (PMID 35928897, 2022). "A large population-based comprehensive cohort study evaluated the association between diabetes in the mother (diabetes with insulin treatment, non-insulin treated diabetes and gestational diabetes), stratified by maternal prepregnancy BMI, and large for gestational age (LGA) at birth." (PMID 36329895, 2022). "In our study, pump users had an earlier age of diagnosis and longer duration of diabetes, which may indicate less residual endogenous insulin secretion and higher risk of hypoglycemia." (PMID 35757419, 2022). "Moreover, they demonstrate that physiologic insulin resensitization can affect several of the untoward manifestations of diabetes and, thus, appears to address the root causes of IR." (PMID 35163806, 2022). "Overall, this Gly40Ser mutation may promote islet β-cell dysfunction, resulting in deficient insulin responses in patients with diabetes." (PMID 35784565, 2022). "Interestingly, as excessive calcium uptake by mitochondria causes damage in neurons in AD, it initiates similar damage also in pancreatic cells, causing insulin malfunctions that lead to diabetes pathologies." (PMID 36232867, 2022). "Furthermore, genetic factors and phenotypical interactions can increase metabolic diabetes risk and contribute to the residual β-cells that cannot adequately control insulin secretion in the right proportions to overcome the insulin resistance state." (PMID 35054924, 2022). "Diabetes mellitus, commonly known as diabetes, is a metabolic disorder that elevates the glucose percentage in the blood, caused by a dysfunction in the production (type-1) or effectiveness (type-2) of insulin in the body." (PMID 35323436, 2022). "Alterations to the gut microbiome of the human host are purported to result from helminth infection, and these may reduce the risk of diabetes by modulating glucose uptake, inflammation, and insulin sensitivity." (PMID 35206272, 2022).
diabetes (continued). "When patients with diabetes fast, reduced glucose intake suppresses insulin secretion however there is underlying pathophysiology of insulin deficiency and/or insulin resistance and thus potentially greater degree of hepatic gluconeogenesis, glycogenolysis and ketogenesis." (PMID 35813638, 2022). "Overweight and obesity are risk factors for diabetes that might be explained by the insulin resistance, type 2 diabetes in obese people, insulin sensitivity, and β-islet cells’ adjust ability declining." (PMID 35270682, 2022). "Diabetes is a metabolic disorder characterized by hyperglycemia resulting from an absolute deficiency of insulin secretion (type 1 diabetes, T1D), or a combination of insulin resistance and an inadequate compensatory insulin secretion (type 2 diabetes, T2D)." (PMID 35784565, 2022). "Diabetes mellitus is one of the most common metabolic disorders caused by either defective insulin secretion by pancreatic β-cells or the inability of insulin-sensitive tissues to respond appropriately to insulin." (PMID 36569665, 2022). "Many people with diabetes experience hypoglycemia of unknown origin; some of these cases might be caused by a deliberate overdose of insulin in an attempt at suicide." (PMID 35324747, 2022). "Diabetes mellitus is a common metabolic disease characterized by persistently high blood sugar levels resulting from a defect in insulin production (type 1) or a deficiency in insulin production/utilization (type 2)." (PMID 36613929, 2022). "People at risk of diabetes may have impairments in multiple processes such as islet development, islet function, autoimmunity, inflammation, insulin sensitivity, incretin activity and adipose tissue function (considered as ‘base colours’)." (PMID 34981134, 2022). "Regarding the potential mechanisms accounting for these reported associations between age at menopause and diabetes, prior studies have proposed that the adverse effects on insulin and glucose levels induced by both short and prolonged endogenous estrogen exposure should be considered." (PMID 35123520, 2022). "Among the four genes (PHIP, TRPM3, SPTY2D1 and TSPO) associated with fasting insulin and combined into a genetic risk score, we showed that carriers of insulin increasing risk alleles had higher odds of developing diabetes and impaired fasting glucose at follow-up." (PMID 35665752, 2022). "The aim of this study was to investigate the impact of anti-diabetic agents on Alzheimer’s disease progression and the levels of Alzheimer’s biomarkers in a hyperglycaemic rat model, which was induced by intraperitoneal injection of streptozocin to produce insulin-deficient diabetes." (PMID 35802659, 2022). "Intermittent fasting, time‐restricted feeding, caloric restriction, and carbohydrate restriction positively modify risk factors in diabetes, including reducing hyperinsulinemia, increasing insulin sensitivity, improving β‐cell responsiveness, and lowering the levels of circulating glucose." (PMID 34921686, 2022). "As diabetes can be exacerbated by oxidative stress, it is essential to provide timely periodontal treatment, given that pathogenic bacteria in periodontal tissues have the potential to impair insulin sensitivity or production." (PMID 36551903, 2022). "Increased FPG, HbA1c, and insulin increased the risk of diabetes among adolescents." (PMID 36010139, 2022). "Leptin antagonizes insulin, thereby causing the breakdown of insulin receptors, lowering insulin sensitivity, and elevating glucose synthesis, which subsequently leads to the development of obesity and diabetes mellitus." (PMID 36232660, 2022). "In the animal trials of INS mutation-induced diabetes, early insulin treatment was shown to protect mice against insulin resistance, α-cell hyperfunction, β-cell loss, and non-β-cell hyperplasia, which seems to give a significantly better prognosis than treating with oral sulfonylureas." (PMID 36686471, 2022).
diabetes (continued). "Previous studies have confirmed that Akkermansia can reduce the risk of diabetes, obesity, and inflammation by reducing the fat formation and inhibiting insulin, which may be a reason for the lower weight of lambs in the LW group." (PMID 36187995, 2022). "It was also clear that, despite the lack of a 2 h and 4 h postprandial blood draw, sufficient resolution existed in the sampling design to identify phenotypic variation in postprandial insulin patterns that have been associated with the detection of occult diabetes." (PMID 35634390, 2022). "The reason for this may be that, on the one hand, participants with a high BMI and high WC may have low muscle mass and thus a higher risk of developing diabetes, considering muscle tissue sensitivity to insulin." (PMID 35257014, 2022). "Insufficiency of insulin due to loss of functional beta-cells results in diabetes." (PMID 35602600, 2022). "Sulfonylureas are usually effective for several decades, but in patients with severe insulin deficiency or after a long duration of diabetes (>11years), insulin treatment may eventually become necessary, either alone or on top of sulfonylureas." (PMID 35052457, 2022). "Diabetes during pregnancy is associated with elevated maternal insulin, leptin and IL-6." (PMID 35197933, 2022). "Diabetes is characterized by the presence of increased proinflammatory cytokines, being IL-1β one of the main inflammatory markers associated in the reduction of insulin signaling leading to insulin resistance in GDM." (PMID 35303833, 2022). "Some of the suggested pathophysiological mechanisms underlying cognitive decline in diabetes patients include hyperglycemia, insulin resistance and altered insulin signaling, neuroinflammation, cerebral microvascular injury, and buildup of cerebral amyloid and tau proteins." (PMID 35682821, 2022). "Diabetes is a chronic illness caused by insulin resistance or poor insulin production." (PMID 35627961, 2022). "Another study in North America and Europe reported a positive association between fish intake and risk of diabetes which may be due to environmental contaminants in fish such as dioxins and methyl mercury which may interfere with insulin signaling pathways." (PMID 35845792, 2022). "Elevated blood glucose levels (hyperglycemia) are observed in diabetes and may be indicative of insulin resistance or deficient insulin secretion." (PMID 35563135, 2022). "Indeed, cholecalciferol supplementation has been reported to be associated with improved peripheral insulin sensitivity and secretion in patients at high risk of diabetes or with type 2 diabetes." (PMID 35267948, 2022). "In fact, by understanding that insulin mediates the process of the pathology of diabetes via obesity, the primary target of diabetes prevention in high-risk communities should be targeting insulin and other inflammatory biomarkers, allowing for early diagnosis and treatment." (PMID 35757631, 2022). "Type 2 diabetes mellitus (T2DM), previously referred to as noninsulin-dependent diabetes or adult-onset diabetes and accounting for 90%–95% of all diabetes, is a disease caused by a gradual decrease in insulin secretion from β cells in the context of insulin resistance." (PMID 35909507, 2022). "It is important to note that FLAIS was related to all CVD risk factors also in the group with prediabetes/diabetes and the correlations coefficients were slightly higher or comparable to the correlations observed for the indices based on blood glucose and insulin concentrations." (PMID 35439985, 2022). "Diabetes mellitus (DM) is a metabolic malady featured by hyperglycemia as a result of a variety of cellular and hormonal disorders including deficiency in insulin production or resistance to insulin action, or both." (PMID 35688972, 2022). "Similarly, diabetes was independently associated with sarcopenia because of the fact that insulin resistance leads to muscle breakdown." (PMID 34383112, 2022).